EFCAB9 (EF-hand calcium binding domain 9)
Description:
Auxiliary component of the CatSper complex, a complex involved in sperm cell hyperactivation. pH-dependent Ca(2+) sensor required to activate the CatSper channel. Sperm cell hyperactivation is needed for sperm motility which is essential late in the preparation of sperm for fertilization. Associates with the CatSper complex via direct interaction with CATSPERZ, and senses intracellular Ca(2+). Together with CATSPERZ, associates with the CatSper channel pore and is required for the two-row structure of each single CatSper channel.
Tractability: No criterion of Open Targets' tractability assessment is met for any kind of drug.
Gene: Protein-coding gene on chromosome 5 (172,194,172 to 172,203,454, forward strand). Ensembl gene ENSG00000214360.
Subcellular location: Cytoplasm; Cell projection, cilium, flagellum
Gene Ontology:
Molecular function: calcium ion binding; calcium ion sensor activity
Biological process: flagellated sperm motility; sperm capacitation; spermatogenesis
Cellular component: CatSper complex; cytoplasm; sperm principal piece; motile cilium
Genetic constraint (gnomAD): Loss-of-function variants: 16 observed, 16.24 expected, observed/expected ratio (o/e) 0.99, 90% interval 0.67 to 1.49. The upper end of that interval is the gene's LOEUF score, 1.49, which puts it in group 6 of 6, group 1 being the genes least tolerant of losing a copy. Missense variants: 208 observed, 244.25 expected, observed/expected ratio (o/e) 0.85, 90% interval 0.76 to 0.95. Synonymous variants: 76 observed, 88.18 expected, observed/expected ratio (o/e) 0.86, 90% interval 0.71 to 1.04.
Homologues: Orthologues: chimpanzee EFCAB9 (98% identical), macaque EFCAB9 (92% identical), rabbit EFCAB9 (73% identical), dog EFCAB9 (70% identical), pig EFCAB9 (70% identical), rat Efcab9 (68% identical), mouse Efcab9 (66% identical), guinea pig EFCAB9 (62% identical), Caenorhabditis elegans B0563.7 (18% identical), Caenorhabditis elegans cal-3 (16% identical), Caenorhabditis elegans cal-1 (16% identical), Caenorhabditis elegans tnc-2 (16% identical), and 4 more. Paralogues in human: CALM1 (19% identical), CALM2 (19% identical), CALM3 (19% identical), CETN1 (19% identical), CETN2 (18% identical), CETN3 (18% identical), CALML3 (18% identical), EFCAB7 (18% identical), CALML4 (16% identical), CALML5 (16% identical), EFCAB12 (16% identical), CABP2 (15% identical), and 8 more.